MED24 (mediator complex subunit 24)
Description:
Component of the Mediator complex, a coactivator involved in the regulated transcription of nearly all RNA polymerase II-dependent genes. Mediator functions as a bridge to convey information from gene-specific regulatory proteins to the basal RNA polymerase II transcription machinery. Mediator is recruited to promoters by direct interactions with regulatory proteins and serves as a scaffold for the assembly of a functional preinitiation complex with RNA polymerase II and the general transcription factors.
Synonyms: ARC100; Trap100; DRIP100; CRSP4; KIAA0130; THRAP4; CRSP100; MED5
Tractability: Small molecule: a structure with a bound ligand is known. PROTAC: ubiquitination databases record sites on it; its protein half-life has been measured.
Gene: Protein-coding gene on chromosome 17 (40,019,097 to 40,061,215, reverse strand). Ensembl gene ENSG00000008838.
Subcellular location: Nucleus
Pathways (Reactome):
Gene expression (Transcription): Generic Transcription Pathway; MLL4 and MLL3 complexes regulate expression of PPARG target genes in adipogenesis and hepatic steatosis
Developmental Biology: Transcriptional regulation of white adipocyte differentiation
Disease: RSV-host interactions
Metabolism: PPARA activates gene expression
Gene Ontology:
Molecular function: nuclear thyroid hormone receptor binding; protein binding; transcription coactivator activity; transcription coregulator activity; nuclear vitamin D receptor binding
Biological process: positive regulation of DNA-templated transcription; positive regulation of transcription initiation by RNA polymerase II; positive regulation of transcription elongation by RNA polymerase II; RNA polymerase II preinitiation complex assembly
Cellular component: core mediator complex; nucleus; mediator complex; nucleoplasm
Genetic constraint (gnomAD): Loss-of-function variants: 74 observed, 118.03 expected, observed/expected ratio (o/e) 0.63, 90% interval 0.52 to 0.76. The upper end of that interval is the gene's LOEUF score, 0.76, which puts it in group 3 of 6, group 1 being the genes least tolerant of losing a copy. Missense variants: 1,041 observed, 1,301.2 expected, observed/expected ratio (o/e) 0.8, 90% interval 0.76 to 0.84. Synonymous variants: 521 observed, 531.94 expected, observed/expected ratio (o/e) 0.98, 90% interval 0.91 to 1.05.
Homologues: Orthologues: chimpanzee MED24 (100% identical), macaque MED24 (99% identical), dog MED24 (96% identical), pig MED24 (96% identical), rabbit MED24 (96% identical), rat Med24 (95% identical), mouse Med24 (94% identical), guinea pig MED24 (93% identical), tropical clawed frog med24 (77% identical), zebrafish med24 (76% identical), Drosophila melanogaster MED24 (29% identical).
Diseases named in the same sentence as MED24 in open-access papers:
MED24 is named in the same sentence as 14 diseases in open-access papers, as found by Europe PMC text mining. Sharing a sentence is not in itself a finding about the gene and the disease. The quoted sentences say what the papers report.
breast carcinoma (9 papers, 2012 to 2025). "It has been shown that MED23 knock‐down promotes tumorigenicity and inhibits apoptosis through a decrease of BAX expression, yet conversely, MED24 knock‐down in breast carcinoma cells lead to diminished cell proliferation and DNA synthesis." (PMID 38831555, 2020). "MED24 is related to the phenotype of breast cancer as well as a bad prognosis for patients." (PMID 40384436, 2025). "MED24 has been reported to have a function in the growth of breast cancer cells." (PMID 35902644, 2022). "It is reported that MED24 is overexpressed in breast cancer cells." (PMID 27192115, 2016). "The large majority (10/13) of these genes were reported to play a role in the regulation of estrogen and/or progesterone response in human breast cancer (NCOA7:; NCOA3:; USP22:; MED24:; CCAR1:; CRY2:; STAT5B:; PAGR1:; TAF1:; PHB2:)." (PMID 35996163, 2022). "The MED1/MED24 complex was previously found to be frequently and simultaneously over-expressed in FBC and to play an important role in the growth of breast cancer cells via the RAS-mitogen-activated protein kinase (MAPK) pathway." (PMID 25906114, 2015). "Multiple other genes from the driver subnetworks, including GRB2, MED1, MED24, and EPN3 are also located in the proximity of the same amplicon (between 17q12–25), underscoring the significance of this chromosomal region in HER2+ breast cancer." (PMID 22343619, 2012).
asthma (2 papers, 2023 to 2024). "Among the protein-coding genes causally associated with unspecified asthma in lung and blood, seven are within the 17q12-21 locus (i.e., PGAP3, IKZF3, GSDMB, ORMDL3, GSDMA, MED24, and CASC3)." (PMID 39628479, 2024). "After applying the Bonferroni correction (Psmr < 2.08 × 10–6) and HEIDI threshold (PHEIDI > 0.01), a total of four SMR genes were identified: three SMR genes (AHI, MED24, and DDX5) with the European asthma-GWAS summary and one SMR gene (RPS26) with the Japanese asthma-GWAS summary." (PMID 37875944, 2023). "Among the four SMR genes in the asthmatic eQTL data, two genes, DDX5 and MED24, were not identified in the SMR analysis of the two normal eQTL data, and have not been reported to be significantly associated with asthma in the SMR analysis." (PMID 37875944, 2023).
colon cancer (2 papers, 2010 to 2023). "The MED24 (mediator complex subunit 24) gene acts indirectly on VDR, a 4T1-upregulated gene in our data, which functions to inhibit p38 activity – a known mediator of tumor cell death in colon cancer." (PMID 20700505, 2010).
bile duct carcinoma (1 paper, 2025). "Similarly, in humans, Mediator subunits MED12, MED14, MED23, and MED24 interact with YAP in bile duct carcinoma cells." (PMID 39752503, 2025).
Cirrhosis (1 paper, 2019). A chronic disorder of the liver in which liver tissue becomes scarred and is partially replaced by regenerative nodules and fibrotic tissue resulting in loss of liver function. "In addition, we also found that MED24, FOXD2 and ZNF282 are associated with the progression from cirrhosis to HCC." (PMID 31811111, 2019).
liver cancer (1 paper, 2016). An epithelial or non-epithelial malignant neoplasm that arises from the liver. "In contrast, an isolated MED24 overexpression was detected in liver cancer (100%, n = 99/99)." (PMID 27050271, 2016).
lung adenocarcinoma (1 paper, 2019). A carcinoma that arises from the lung and is characterized by the presence of malignant glandular epithelial cells. "MED24 not only had the highest correlation relationship (R-value) with ERBB2 in lung adenocarcinoma and in SCC, but also had a significant fold change after Erbb2 loss in mouse lungs." (PMID 31248101, 2019).
lung carcinoma (1 paper, 2019). "We found inhibition of MED24 expression in human lung cancer cells (e.g., H358) using siRNA-reduced cell growth." (PMID 31248101, 2019). "Clinically, MED24 expression is associated with a poor survival rate of NSCLC patients, suggesting MED24 as a potential target for lung cancer patients, especially those with ERBB2 alterations." (PMID 31248101, 2019). "Meanwhile, we noticed that the impact of MED24 knockdown on lung cancer cell growth is limited." (PMID 31248101, 2019). "We hypothesized that these top ERBB2-correlated genes, such as MED24, were crucial players regulating lung cancer development." (PMID 31248101, 2019). "MED24 may be a critical gene required for cell growth of lung cancer cells." (PMID 31248101, 2019). "In line with these oncogenic characteristics of MED24 in human lung cancer cells, we found that NSCLC patients with MED24 high expression had a lower survival rate." (PMID 31248101, 2019). "We not only identified that MED24 is a conserved downstream gene of ERBB2 in mouse and human lung tumors but also showed that its knockdown attenuates cell growth of lung cancer cells." (PMID 31248101, 2019). "Functional analysis of the top ERBB2-correlated genes (e.g., MED24) suggested that overexpression of MED24, a subunit of the Mediator complex, might be required for the ERBB2 pathway to dysregulate gene expression and the consequent lung cancer development." (PMID 31248101, 2019).
myeloid leukemia (1 paper, 2024). A clonal proliferation of myeloid cells and their precursors in the bone marrow, peripheral blood, and spleen. "Indeed, the pleiotropic gene set was found to have an overrepresentation of regulators of myeloid leukemia: DOT1L, EP300, FLI1, GSE1, and MED24 (OR = 7.1; phypergeometric = 4 × 10−4)." (PMID 38308367, 2024).
viral infection (1 paper, 2022). "The occurrence of it may be related to MYC, P63, and MED24 as well as Wnt, MAPK, and PI3K signaling pathways, but it has no connection with environmental factors and viral infection, such as Epstein-Barr virus and human papillomavirus." (PMID 36687409, 2022).
cancer (5 papers, 2012 to 2025). A tumor composed of atypical neoplastic, often pleomorphic cells that invade other tissues. "Taken together, ERBB2 is required for the dysregulation of cancer-related genes, such as MED24, during lung tumor development." (PMID 31248101, 2019). "MED24, encoding a subunit for the mediator complex of RNA polymerase II, is known to be a downstream target of HER2 and may be a critical gene required for cancer development." (PMID 36661191, 2023).
tumor (2 papers, 2010 to 2011). "There were two genes, in addition to HER2, clearly overexpressed in HER2+ tumours, GRB7 and MED24, which are both upstream of ERBB2 on chromosome 17 and previously associated with the HER2+ subtype." (PMID 22067903, 2011).
MED24 also shares sentences with these, for which no sentence is quoted: glioma (2 papers); pterygium (1).